VAV1 (vav guanine nucleotide exchange factor 1)
Diseases named in the same sentence as VAV1 in open-access papers (continued):
Sharing a sentence is not in itself a finding about the gene and the disease.
tumor (continued). "Despite these observations, we do not consider that the putative tumor suppressor activity of RasGRF2 is a plausible explanation for the results reported here, because the Rasgrf2 deficiency only contributes to tumorigenesis when combined with the Vav1 proto–oncogene loss." (PMID 20011522, 2009). "In particular, VAV1 has been shown to have tumor suppressor functions in TLX+ T cell receptor‐negative T cell acute lymphoblastic leukemia and both protumorigenic and tumor suppressor roles in peripheral T cell lymphoma." (PMID 39119789, 2025). "However, G-5555 partially re-sensitized Rac1-driven BRAFi-resistant tumor cells to BRAF inhibition, both for Vav1 over-expressing cells and for cells expressing the clinically relevant Rac1 P29S constitutively active mutant." (PMID 41109929, 2025). "Given the structural similarity and overlapping functions of VAV proteins, it is plausible that VAV3 may also play tumor suppressor roles akin to VAV1." (PMID 39200159, 2024). "Our experiments with transgenic mice expressing Vav1 in the pancreas demonstrated that the mere expression of Vav1 in this organ does not lead to tumor formation." (PMID 35326399, 2022). "In HPAF-2, as observed in HPAF-I and in other tumor cells, ATRA induced a partial epithelial re-differentiation, that we have found almost entirely determined by the presence of adequate levels of Vav1." (PMID 33165749, 2021). "No reports confirm this classification of Vav1 as a potential tumor suppressor in T cells nor has it yet been shown in other cancers, especially in solid tumors of epithelial origin." (PMID 30297765, 2018). "Tumor masses, detected starting from the second week after injection, reached a significantly lower dimension in mice receiving MDA‐MB‐231 cells overexpressing Vav1 compared to those derived from MDA‐MB‐231 transfected with an empty vector." (PMID 29658179, 2018). "We focused the subsequent analyses on the “common” gene signature class, since we surmised that it could give clues about the transformation process of both the Vav1−/− DN and CD8+ tumor subpopulations." (PMID 29136506, 2017). "This resemblance is not due to the activation of programs common to most cancer cells because the Vav1−/− tumor gene signature does not overlap with the transcriptome of tumor T cells obtained from mice defective in tumor suppressors such as Pten and Cdkn2a." (PMID 29136506, 2017). "By immunohistochemical analysis on TMAs containing invasive breast tumor from patients without lymph node involvement, we have found that Vav1 is expressed in almost all investigated cancers and shows a peculiar localization inside the nucleus of tumor cells." (PMID 24962430, 2014). "Immunoreactivity for Vav1 was found primarily in the nucleus of tumor cells, with or without concomitant cytoplasmic staining." (PMID 24962430, 2014). "Our study reveals that Vav1 and CSF1 influence the activity of each other and are engaged in an autocrine mechanism that could enhance tumor growth." (PMID 25313137, 2014). "Nucleotide sequence analysis revealed that the Vav1 oncogene was activated in vitro and the isolated mutant form was not present in the original tumor sample." (PMID 22253833, 2012). "To this end, we first used a standard bioinformatics comparison tool available in that database to investigate whether the expression of VAV1 and/or RASGRF2 genes was deregulated in hematopoietic tumor cells relative to their normal cell counterparts." (PMID 20011522, 2009). "Levels of Vav 1 and TIAM-1 were also higher in tumours but were not significantly different (0.66 ± 0.35 v 0.07 ± 0.027; p = 0.095 for Vav1 and 1196 ± 743 v 261 ± 107; p = 0.22 for TIAM-1)." (PMID 18925966, 2008). "This is the only VAV1 GEMM to show tumor development without additional molecular lesions, suggesting that VAV1 alone may lead to tumor development under certain circumstances." (PMID 37174676, 2023).
tumor (continued). "The question is whether the mere overexpression of Vav1 in certain cells of non-hematopoietic origin suffices to lead to tumor development." (PMID 35326399, 2022). "Importantly, mice lacking Vav1 have diminished cytolytic activity against several tumor targets but retain the ability to produce cytokines." (PMID 31143782, 2019). "Overexpression of Vav1 in multiple tumor types is known to enhance oncogenicity, yet whether or not Vav1 is a bona fide oncogene is still a matter of debate." (PMID 30297765, 2018). "To date, these oncogenic forms of Vav1 have never been found in neoplasms." (PMID 25426554, 2015). "Instead, we could not detect any patient tumor subgroup showing upregulation of VAV1 relative to the total patient cohort." (PMID 20011522, 2009). "However, the lack of tumour formation in other haematopoietic cell types might be the consequence of the rewiring of the developmental path of some cell lineages by oncogenic VAV1." (PMID 35895495, 2022). "However, unlike the case of Vav1, there is evidence indicating that it may also exert some tumor–suppressor activities." (PMID 20011522, 2009). "We cannot rule out a putative Vav1-dependent cooperation between AP1 and β-catenin to regulate tumour progression and further work is needed to address this point." (PMID 25426554, 2015). "The role of Vav1 in modulating the expression of a focused panel of genes involved in tumor progression was investigated in the non-metastatic BT-474 and in the moderately metastatic MDA-MB-231 cells, both showing high amounts of Vav1 at nuclear level." (PMID 24962430, 2014). "Vav1 is ectopically expressed in a number of non-hematopoietic cancers, including PDAC, in which this protein seems to be involved in signal transduction processes correlated with aggressive tumor phenotypes." (PMID 32993067, 2020). "Lack of both Vav1 and CSF1 correlated with lower tumor grade (p<0.05)." (PMID 25313137, 2014). "Finally, immunohistochemistry (IHC) images of human tissue samples obtained from the Human Protein Atlas show no staining of VAV1 in a normal pancreas, whereas a PDAC tissue sample showed staining for VAV1, with signal occurring in both nuclear and cytoplasmic compartments of tumor cells." (PMID 41314543, 2025).
cancer (53 papers, 2007 to 2026). A tumor composed of atypical neoplastic, often pleomorphic cells that invade other tissues. "Further understanding of the mechanism underlying the oncogenic function of VAV1 is of great biological importance as it can help improve future therapeutic efforts for cancer patients." (PMID 41314543, 2025). "For example, why are there distinct differences in VAV1 mutations in hematopoietic malignancies compared to all other cancers?" (PMID 37174676, 2023). "Data collected on VAV1 presence and involvement in human cancers, either as an overexpressed or mutated protein, suggest that it is an oncogene, as presented below." (PMID 37174676, 2023). "Systematic interrogation of the broad spectrum of Vav1 mutations (and translocations) observed in many cancer types suggest that approximately 50% of Vav1 mutations are non-functional passenger mutations." (PMID 36845711, 2023). "Mutations and overexpression of Vav1 in hematopoietic malignancies, and in human cancers of various histologic origins, are well documented." (PMID 35326399, 2022). "The most common GEFs implicated in cancer are T-cell lymphoma invasion and metastasis 1 (Tiam1), Trio, Vav1/2/3, Ect2, Phosphatidylinositol 3,4,5-trisphosphate (PIP3)-dependent Rac exchanger 1 (P-Rex1), and Dock1." (PMID 32322580, 2020). "Studies demonstrated that mutations like E59K and D517E are highly transforming indicating that specific mutations of VAV1 can be recognized as a bona fide oncogene in human cancers." (PMID 31027363, 2019). "VAV1 mutations have been identified in human cancers of various origins in the context of different oncogenic phenotypes." (PMID 31027363, 2019). "Although mutations in Vav1 were recently identified in human cancers of various origins, the functional activities of these mutants are not known." (PMID 30297765, 2018). "Several Vav1 mutations in cancer occur at highly conserved residues in the SH2 domain, including R678Q, E682E, G691R, and R696W." (PMID 26353933, 2015). "Further research is required to provide more definitive insight into mechanisms underlying Vav1's role in human cancer." (PMID 26353933, 2015). "To investigate the mechanisms underlying tissue-specific and cancer-related transcription of vav1, we used a reporter gene approach." (PMID 22253833, 2012). "Mutations in VAV1 identified in human cancers involve all major domains." (PMID 37174676, 2023). "From the time that Vav1 was first identified as an oncogene (oncVav1), a question has remained as to whether it is mutated in human cancers, thus acting as a “real” oncogene." (PMID 30297765, 2018). "Mutations in Vav1 identified in human cancers span all of its cardinal domains." (PMID 30297765, 2018). "While evidence over the last decade substantiated Vav1 overexpression in human cancer, the question remained whether mutations in Vav1 contribute to human cancers." (PMID 26353933, 2015). "The newly identified mutations in Vav1 in human cancer will be discussed." (PMID 26353933, 2015). "Whether these experiments point to a possible dual role of Vav1 in cancer, depending on the specific mutation and the specific cell-type, remains to be carefully studied." (PMID 26353933, 2015). "The mutations identified in Vav1 in human cancer span all its cardinal domains." (PMID 26353933, 2015). "Vav1 was recently implicated in several human cancers, including lung, pancreatic and neuroblasoma." (PMID 23342133, 2013). "Despite the reports on the involvement of Vav1 in human cancer, either as a mutated gene or an abnormally expressed gene, little work has been conducted to decipher its involvement in the development of cancer by using genetically engineered mouse models (GEMMs)." (PMID 35326399, 2022). "Some cancers exhibit a higher occurrence of Vav1 mutations, such as those originating in the biliary tract (5.17%), endometrium (3.23%), large intestine (4.35%), and skin (6.13%), possibly attesting to the importance of the molecular lesions in Vav1 in certain tissues." (PMID 26353933, 2015).
cancer (continued). "We also focus on what we have learnt on the role of VAV1 in cancer using genetically modified mouse models (GEMMs)." (PMID 37174676, 2023). "The VAV1 promoter is completely unmethylated in human cells but methylated in cancer cells, resulting in its expression." (PMID 37174676, 2023). "VAV1, either as an overexpressed protein or a mutant protein, is present in cancers originating from all tissue types, supporting its designation as a legitimate oncogene." (PMID 37174676, 2023). "We review herein the current knowledge about the various aberrations of VAV1 in human cancer, which suggests that it can be considered an oncogene." (PMID 37174676, 2023). "The mystery was solved, but the following question remained: Is VAV1 a protein involved in human cancer?" (PMID 37174676, 2023). "The expression of genes in NPC tissues and normal tissues was observed, and it was found that the expression of BTK, CD72, PTPN6, and VAV1 was different in cancer and normal tissues, and the expression was lower in both cancer and normal tissues." (PMID 35957889, 2022). "The overexpression of Vav1 in hematopoietic malignancies, and in human cancers of varied histologic origins is well documented." (PMID 35326399, 2022). "Our study is focused on the role of the signal transducer Vav1 in cancer of various histological origins." (PMID 35326399, 2022). "Roles for the third family member, Vav1, in cancer and other pathologies will be described in other reviews of the Special Issue on Vav proteins of this journal." (PMID 34571735, 2021). "As summarized above, this is the first time that the transcriptional repression of VAV1 gene appears to represent a key factor contributing to human cancer pathogenesis." (PMID 34571765, 2021). "Although the physiological activity of Vav1 is well understood, its contribution to human cancer is only starting to emerge." (PMID 32277014, 2020). "Several studies indicated that the activity of Vav1 as a GEF towards Rac1 plays an important role in Vav1’s involvement in cancer." (PMID 32277014, 2020). "The transforming activity of Vav1 mutants detected in human cancers has been tested in only a limited number of studies." (PMID 30297765, 2018). "The physiological activity of Vav1 is fairly well understood, but its contribution to human cancers has only recently started to emerge." (PMID 30297765, 2018). "Many studies over the past decade have reported unexpected expression of the hematopoietic signal transducer Vav1 in a variety of human cancers." (PMID 30297765, 2018). "Vav1 is specifically expressed in human cancer and plays a major role in carcinogenesis and progression, it has been defined as an oncogene." (PMID 28881704, 2017). "It is located on chromosome 19p12-p13.2, the domain of karyotypic abnormalities in human solid tumors or hematopoietic malignancies, therefore Vav1 has an essential function in human cancer." (PMID 28881704, 2017). "This GTPase-independent Vav1 suppressor pathway will be preserved in cancer cells even under conditions of inhibition of Vav1 catalytic activity." (PMID 29136506, 2017). "This review addresses the physiological function of wild-type Vav1 and its activity as an oncogene in human cancer." (PMID 26353933, 2015). "Vav1 functions physiologically in numerous pathways, therefore it is somewhat difficult to attribute its multiple activities in cancer to a particular pathway." (PMID 26353933, 2015). "The ability of Vav1 to contribute to cancer development was recently also attributed to its expression in cells of the microenvironment." (PMID 26353933, 2015). "This review will focus on our recent understanding of the involvement of Vav1 in human cancer, the mechanism of ectopic Vav1 expression in cancer and its mode of function." (PMID 26353933, 2015).
cancer (continued). "The possibility that additional transcription factors play a role in Vav1 expression in cancer cells remains to be explored." (PMID 26353933, 2015). "Nonetheless, the main role attributed to Vav1 in cancer is its activity as a GEF for Rho/RacGTPases." (PMID 26353933, 2015). "Like Vav1, Vav2 and Vav3 become oncogenic following N-terminal truncation, yet there appears to be Vav isoform-distinct functions in cancer." (PMID 26353933, 2015). "One interesting signal transducer protein that is a potential target for cancer therapeutic drugs is Vav1." (PMID 26353933, 2015). "In the past decade numerous studies reported the unexpected expression of Vav1, which is usually found only in the hematopietic system, in a variety of human cancers." (PMID 26353933, 2015). "From the MSigDB Cancer Neighbourhood Ontology, we found that the GM-enriched binding windows were in proximity to cancer-associated genes, CD53, VAV1, INPP5D, STAT6, HLA-C, etc." (PMID 25522020, 2014). "Our studies also provide evidence for the first time for the involvement of Vav1 in a Rac-independent pathway in cancer cells." (PMID 25313137, 2014). "The contribution of Vav1 to human cancer has been shown to stem from its ability to function as a signal transducer in tissues in which it is not normally expressed." (PMID 25313137, 2014). "We assessed Vav1 expression using a commercial human breast tissue array containing 70 cases of reactive, premalignant and malignant tumors of various grades and stages and five normal controls in duplicates." (PMID 23342133, 2013). "Our results highlight a similar role for Vav1, an important player in its own signaling cascade in thymocytes, which contributes to cancer development when aberrantly expressed in the breast." (PMID 23342133, 2013). "Collectively, these results raise the possibility that c-Myb regulates the expression of Vav1 in cancer, thus playing a central regulator of cells invasive properties in some cancer types." (PMID 22253833, 2012). "We also demonstrate the contribution of CpG dinucleotide methylation of the vav1 promoter to its expression in hematopoietic and cancer cells." (PMID 22253833, 2012). "Determining what drives aberrant Vav1 expression in tissues outside the hematopoietic system is important for understanding Vav1's involvement in human cancer." (PMID 22253833, 2012). "In the osteoblasts_Gapd2 subpopulation, pathways such as proteoglycans in cancer (Col1a1, Col1a2, Hcls1, Hif1a, Stat3, Vav1), IL-17 signaling (Mmp13, Mmp3, S100a9, Ccl7, Cebpb), and ECM–receptor interaction (Col11a2, Col1a1, Ibsp, and Tnn) were activated (p < 0.05)." (PMID 41459160, 2025). "To date, the contribution of nuclear VAV1 to cancer development remains poorly understood." (PMID 41314543, 2025). "What have we learnt about VAV1’s function in cancer when it is overexpressed?" (PMID 37174676, 2023). "As epidermal growth factor receptor (EGFR), Vav1, RhoA, Rac1, and BPGAP1 are all associated with cancer metastasis, BPGAP1 could provide a crucial checkpoint for the EGFR-BPGAP1-Vav1-Rac1-RhoA signaling axis for cancer intervention." (PMID 36598812, 2023). "VAV1 has been shown to be a prognostic marker for human cancer." (PMID 37174676, 2023). "Additionally, there are examples of mutants such as D165_174, a deletion mutation that removes 10 amino acids within the DH domain of VAV1, resulting in a decrease in the GEF activity of VAV1, thus inhibiting cancer cell migration and invasion P615L." (PMID 37174676, 2023). "To determine whether unbiased expression of wild-type Vav1 (Vav1) in adult mouse tissues leads to the development of cancer, we generated a Vav1 transgenic mouse line that is driven by the Rosa26 promoter." (PMID 35326399, 2022).